VSTM5 (V-set and transmembrane domain containing 5)
Description:
Cell adhesion-like membrane protein of the central nervous system (CNS) which modulates both the position and complexity of central neurons by altering their membrane morphology and dynamics. Involved in the formation of neuronal dendrites and protrusions including dendritic filopodia. In synaptogenesis, regulates synapse formation by altering dendritic spine morphology and actin distribution. Promotes formation of unstable neuronal spines such as thin and branched types. Regulates neuronal morphogenesis and migration during cortical development in the brain.
Synonyms: C11orf90; LOC387804
Tractability: Antibody: UniProt places it where antibodies can reach, with medium confidence; UniProt predicts a signal peptide or a membrane-spanning region; its Gene Ontology location is reachable by antibodies, with medium confidence.
Gene: Protein-coding gene on chromosome 11 (93,818,232 to 93,850,620, reverse strand). Ensembl gene ENSG00000214376.
Subcellular location: Cell membrane; Cell projection, dendrite; Cell projection, axon
Subcellular location (Human Protein Atlas): Endoplasmic reticulum
Gene Ontology:
Biological process: filopodium assembly; immune response; positive regulation of excitatory synapse assembly; protein homooligomerization; ventral spinal cord development
Cellular component: axon; dendrite; membrane; plasma membrane
Genetic constraint (gnomAD): Loss-of-function variants: 21 observed, 21.12 expected, observed/expected ratio (o/e) 0.99, 90% interval 0.7 to 1.43. The upper end of that interval is the gene's LOEUF score, 1.43, which puts it in group 5 of 6, group 1 being the genes least tolerant of losing a copy. Missense variants: 219 observed, 258.86 expected, observed/expected ratio (o/e) 0.85, 90% interval 0.76 to 0.95. Synonymous variants: 100 observed, 106.33 expected, observed/expected ratio (o/e) 0.94, 90% interval 0.8 to 1.11.
Homologues: Orthologues: chimpanzee VSTM5 (99% identical), macaque VSTM5 (99% identical), pig VSTM5 (92% identical), rabbit VSTM5 (92% identical), mouse Vstm5 (77% identical), dog VSTM5 (76% identical), rat Vstm5 (76% identical), guinea pig VSTM5 (75% identical), tropical clawed frog vstm5 (45% identical), zebrafish si:dkeyp-97a10.3 (14% identical). Paralogues in human: CEACAM1 (22% identical), HEPACAM (22% identical), PSG3 (20% identical), PSG6 (20% identical), PSG4 (20% identical), PSG8 (20% identical), CEACAM5 (19% identical), CEACAM8 (18% identical), PSG11 (18% identical), PSG7 (18% identical), CEACAM16 (18% identical), CEACAM6 (18% identical), and 12 more.
Diseases named in the same sentence as VSTM5 in open-access papers:
VSTM5 is named in the same sentence as 2 diseases in open-access papers, as found by Europe PMC text mining. Sharing a sentence is not in itself a finding about the gene and the disease. The quoted sentences say what the papers report.
major depressive disorder (1 paper, 2017). An episode of depression lasting two or more weeks without an intervening episode of mania. "It is also worth noting that Vstm5 was recently identified as one of the target genes responsible for the differential response to the treatment of major depressive disorder, implying possible roles of Vstm5 in psychiatric diseases." (PMID 28746350, 2017).
VSTM5 also shares sentences with these, for which no sentence is quoted: psychiatric diseases (1 paper).